MPO (myeloperoxidase)
Diseases named in the same sentence as MPO in open-access papers (continued):
Sharing a sentence is not in itself a finding about the gene and the disease.
dysentery (1 paper, 2018). Acute inflammation of the intestine associated with infectious diarrhea of various etiologies, generally acquired by eating contaminated food containing toxins, biological derived from bacteria or other microorganisms. "Biomarkers of intestinal inflammation and injury (methylene blue, fecal occult test, myeloperoxidase or MPO) showed a strong association with dysentery, but mixed results with infection." (PMID 29415075, 2018). "Despite their lower prevalence, C. coli/jejuni were more strongly associated with higher levels of myeloperoxidase, clinical dysentery, and the presence of leukocytes and blood in the stool compared to other Campylobacter." (PMID 29415075, 2018). "Dysentery was still associated with the highest MPO levels (23,163 ng/mL), which were significantly different from MPO levels in the control and severe diarrhea groups (12,333 and 11,970 ng/mL, respectively)." (PMID 29415075, 2018). "MPO data were available for 415 samples and were missing completely at random (169/181 controls, 80/85 dysentery samples, and 166/173 severe diarrhea samples)." (PMID 29415075, 2018). "MPO levels were generally higher among children infected with C. coli/jejuni, but Shigella-infected children suffering from dysentery recorded the highest levels (26,224 ng/mL); the lowest levels (10,625 ng/mL) were among asymptomatic children infected with other Campylobacter." (PMID 29415075, 2018).
Dysmenorrhea (1 paper, 2021). Pain during menstruation that interferes with daily activities. "Second, myeloperoxidase activation plays a role in the association between air pollution and increased incidence of dysmenorrhea." (PMID 34222182, 2021).
eczema (1 paper, 2017). "Mice deficient in MSK1/2 were shown to be more susceptible to endotoxic shock and showed enhanced myeloperoxidase activity following phorbol ester-triggered eczema." (PMID 29039777, 2017).
Endocardial fibrosis (1 paper, 2024). The presence of excessive connective tissue in the endocardium. "While MPO, which is involved in oxidative stress, correlated with endocardial fibrosis, NT-proANP, a marker for atrial wall stress, was associated with LAVI." (PMID 39651434, 2024). "While MPO correlated with endocardial fibrosis, NT-proANP was associated with left atrial volume." (PMID 39651434, 2024). "While MPO correlated with endocardial fibrosis, NT-proANP was associated with LAVI." (PMID 39651434, 2024).
endometrial cancer (1 paper, 2024). Primary or metastatic malignant neoplasm involving the endometrium (mucous membrane that lines the endometrial cavity). "These proteins, along with MPO, were good markers for early endometrial cancer diagnosis." (PMID 39194522, 2024). "Among 52 proteins previously identified by the research team, 8 proteins (MMP9, KPYM, LDHA, CADH1, NAMPT, MPO, ENOA and CAPG) achieved the highest accuracy in diagnosing endometrial cancer in CVF." (PMID 39194522, 2024).
eosinophilic disorders (1 paper, 2023). "Although the precise mechanism of how dupilumab could trigger the development of EGPA requires further elucidation, measuring MPO-ANCA in patients with multiple eosinophilic disorders before the initiation of dupilumab might be helpful when considering the possibility of a latent EGPA." (PMID 37076824, 2023).
epididymo-orchitis (1 paper, 2025). A disorder involving inflammation of the epididymis and testes. "The first case, MPO-ANCA positive, exhibited predominant fibrotic and inflammatory features with ILD and cardiac involvement and was classified as Berden focal class, while the second, PR3-ANCA positive, presented with crescentic class and epididymo-orchitis as a rare manifestation." (PMID 41438740, 2025).
epileptic seizures (1 paper, 2013). "The reduction in MPO by LEV could be linked to its ability to maintain the BBB integrity, where LEV preserves the morphological and functional properties of the BBB together with the reduction of pinocytotic activity during epileptic seizures." (PMID 24098559, 2013).
esophageal adenocarcinoma (1 paper, 2025). A malignant tumor with glandular differentiation arising predominantly from Barrett mucosa in the lower third of the esophagus. "The MPO inhibitor azide reduces increased levels of neutrophil ROS leading to mucosal damage in Barrett’s esophagus, considered a precancerous lesion of esophageal adenocarcinoma." (PMID 41019086, 2025).
esophageal varices (1 paper, 2021). Abnormally dilated veins of the esophagus. "MPO-DNA was significantly higher in patients with ascites (p < 0.01) or esophageal varices (p < 0.01) as compared to patients without these clinical features." (PMID 34504150, 2021).
follicular lymphoma (1 paper, 2024). Follicular lymphoma is a form of non-Hodgkin lymphoma characterized by a proliferation of B cells whose nodular structure of follicular architecture is preserved. "This nanoprobe enabled the simultaneous and quantitative detection of MPO and BCL2 transcripts in bone marrow FFPE infiltrated by follicular lymphoma cells through spectral imaging analysis." (PMID 39273202, 2024).
gallstones (1 paper, 2023). Solid crystalline precipitates in the biliary tract, usually formed in the gallbladder, resulting in the condition of cholelithiasis. "Notably, among the proteins associated with folate metabolism, MPO exhibited a significant increase during gallstone development and mucus layer thickening in a mouse model." (PMID 38111640, 2023).
ganglionitis (1 paper, 2014). "Starting at 110 days, inflammation also appeared at the level of the muscularis propria, demonstrated by elevated MPO-activity and a myenteric ganglionitis." (PMID 25354336, 2014).
gastrointestinal mucositis (1 paper, 2020). "Similarly, vitamin C has been shown to attenuate 5-fluorouracil-induced gastrointestinal mucositis by inhibiting the activation of the NF-κB pathway and by reducing lipid peroxidation and myeloperoxidase (MPO)." (PMID 33383956, 2020).
Glucose intolerance (1 paper, 2021). Glucose intolerance (GI) can be defined as dysglycemia that comprises both prediabetes and diabetes. "Metformin, used in 45% of our patients (not only with glucose intolerance), likely also contributed to MPO reduction by modulating ROS production by WBCs and its direct modulation effect on hydroxyl radical superoxide anion production." (PMID 34202775, 2021). "We aimed to determine whether MPO and SOD modification are proportional to the loss of fat mass or body weight, or are glucose intolerance dependent." (PMID 34202775, 2021). "Conversely, MPO reduction was paralleled by diminishing neutrophil counts, which was mainly observed after marked weight loss and in patients without glucose intolerance, also suggesting a reduced MPO expression by the leukocyte defence system." (PMID 34202775, 2021). "Our results showed that MPO was markedly reduced after weight loss, despite the fact that its reduction was not related to the proportion of fat mass and body weight loss and was not connected to glucose intolerance." (PMID 34202775, 2021). "Patients who lost a small amount of fat mass, body weight and had glucose intolerance also exhibited MPO reduction, which was not paralleled by a decrease in neutrophil count." (PMID 34202775, 2021). "The decline in MPO was independent of whether patients lost high or low-fat mass, high or low body mass, and whether the patients had or did not have glucose intolerance." (PMID 34202775, 2021).
granulomatous dermatitis (1 paper, 2023). An inflammatory reaction of the skin to various organic and inorganic antigens. "The myeloperoxidase anti-neutrophil cytoplasmic antibody (MPO-ANCA) test was positive, and the young patient gradually developed palisaded neutrophilic and granulomatous dermatitis (PNGD), orbital and paranasal sinus granulomatous neoplasms, along with intermittent nose, head, and orbital pain." (PMID 37492611, 2023).
hemochromatosis type 1 (1 paper, 2016). Hemochromatosis type 1 (classic) is the most common form of hereditary hemochromatosis (HH), a group of diseases characterized by excessive tissue iron deposition. "The enrichment overlaps included a known pathogenic missense variant in myeloperoxidase deficiency (MPO), and we identified additional known pathogenic variants in uncurated genes including CX3CR1 (HIV progression) and hemochromatosis type 1 (HFE)." (PMID 27863252, 2016).
hidradenitis suppurativa (1 paper, 2024). A chronic suppurative and cicatricial disease of the apocrine glands occurring chiefly in the axillae in women and in the groin and anal regions in men. "Variants involved the TLR2 and MPO genes in the first family and the MMP2, GJB2, and TLR4 genes, some of which have already been previously reported as possible candidates for hidradenitis suppurativa." (PMID 39595064, 2024).
hip fracture (1 paper, 2025). Traumatic or pathological injury to the hip in which the continuity of either the femoral head, femoral neck, intertrochanteric or subtrochanteric regions is broken. "Hip fracture patients had significantly higher serum concentrations of cell-free DNA, MPO-DNA and CitH3 (all P < 0.01), and numerically higher cell-free DNA in CSF (P = 0.063) compared to cognitively healthy controls." (PMID 39737468, 2025). "Cell-free DNA, CitH3 and MPO-DNA were higher in serum of hip fracture patients than healthy controls." (PMID 39737468, 2025).
Histiocytosis (1 paper, 2017). An excessive number of histiocytes (tissue macrophages). "Therefore, the first attempt to characterize the skin biopsy fragments was made, a diagnosis of Lanherhans Cells Histiocytosis was discussed, based on CD68+++, CD 45+, MPO+, CD1a-, S-100-, desmin -, MY14-." (PMID 29450403, 2017).
HIV-1 infection (1 paper, 2010). The type species of lentivirus and the etiologic agent of acquired immunodeficiency syndrome (AIDS). "Adding MPO to PMN-(MPO-deficient) cell cultures restored the ability to block HIV-1 infection." (PMID 20525179, 2010).
Hyponatremia (1 paper, 2023). An abnormally decreased sodium concentration in the blood. "Other markers that have been evaluated include mean platelet volume (MPV), white blood cell (WBC) count, ESR, red cell distribution width (RDW), Pentraxin-3, hyponatremia, and oxidative markers such as nitric oxide and myeloperoxidase, to name a few." (PMID 37685553, 2023).
hypovitaminosis D (1 paper, 2024). "According to our results, hypovitaminosis D (independently of BMI status) was associated only with increased adiponectin levels and not with other biomarkers of inflammation and oxidative stress (WBC counts, CRP, MCP-1, MPO, I-TAC, SOD-1)." (PMID 39408928, 2024).
immunotoxicity (1 paper, 2024). "Deltamethrin exposure stimulates the formation of extracellular traps by elevating the levels of myeloperoxidase (MPO) and reactive oxygen species (ROS) along with mitochondrial dysfunctioning leading to immunotoxicity in Manila clam (Ruditapes philippinarum) hemocytes." (PMID 39239465, 2024).
infectious colitis (1 paper, 2012). A viral or bacterial infectious process affecting the large intestine. "BC30 also significantly attenuated histological and biochemical indices (MPO) of infectious colitis." (PMID 23088680, 2012).
intrauterine growth restriction (1 paper, 2025). "A study evaluating patients with PE + intrauterine growth restriction showed significantly higher plasma MPO levels before delivery in this group than in healthy pregnant women." (PMID 40806204, 2025).
irritant dermatitis (1 paper, 2020). An inflammatory skin condition caused by direct contact between the skin and an irritating substance. "In this study, LCZ significantly inhibited ear swelling associated with TPA‐induced irritant dermatitis in mice at concentrations of more than 1%, and LCZ dose‐dependently and remarkably suppressed the increases in the MPO activity, KC content and MIP‐2 content in TPA‐induced irritant dermatitis." (PMID 31724251, 2020).
ischemic cardiomyopathy (1 paper, 2022). Ischemic cardiomyopathy is a cardiomyopathy in which a weakness in the muscle of the heart due to inadequate oxygen delivery to the myocardium with coronary artery disease being the most common cause. "The crucial question we addressed in this context was whether therapeutic MPO inhibition could reduce the increasing incidence of ischemic cardiomyopathy and HF after MI due to their enormous impact on the healthcare system in western countries." (PMID 36670895, 2022).
jejunoileitis (1 paper, 2018). "In this study, MTX injections triggered jejunoileitis in SD rats which in turn elicited marked histological alterations and an increase in MPO activity." (PMID 29862296, 2018).
Klebsiella pneumonia (1 paper, 2023). An pneumonia caused by infection with Klebsiella. "Established Klebsiella pneumonia increased mRNA concentrations of Collagen I and VI and ICAM 1 and lung myeloperoxidase." (PMID 37469663, 2023).
left ventricular hypertrophy (1 paper, 2022). Enlargement of the LEFT VENTRICLE of the heart. "Finally, we found that MPOprotein was expressed in healthy adult murine and human cardiomyocytes, and MPO levelswere increased in diseased hearts with left ventricular hypertrophy." (PMID 33705529, 2022).
limb ischemia (1 paper, 2023). A ischemia that involves the limb. "In a recent prospective cohort study on patients with PAD, CAD, or both, rates of all-cause mortality and MACE increased with increasing MPO levels, whereas MPO was associated with rates of limb ischemia and further revascularization in patients with PAD." (PMID 36674682, 2023).
lipid metabolic disorders (1 paper, 2021). "Second, we found that SARS-CoV-2 infection could modulate the expression of MPO, apelin, and myostatin by up-regulating transcription factor REST, which may lead to glucose and lipid metabolic disorders." (PMID 34916489, 2021).
lymphoma of the ovary (1 paper, 2023). "MRI features of lymphoma of the ovary include the presence of bilateral homogeneous solid masses with mild, homogenous enhancement and rather low T2 signals, due to the presence of myeloperoxidase." (PMID 37046767, 2023).
male infertility (1 paper, 2024). The inability of the male to effect fertilization of an ovum after a specified period of unprotected intercourse. "Given that oxidative stress is a common pathology encountered in male infertility, recent research has attempted to delve into the role of MPO in male infertility." (PMID 39226216, 2024).
medullary thyroid cancer (1 paper, 2025). "IF images showed concomitant staining reductions of both H3Q5ser and H3cit in MPO+ neutrophils in metastasis–containing liver sections from SCLC and medullary thyroid cancer models." (PMID 39903533, 2025).
mental disorder (1 paper, 2025). A disease that has its basis in the disruption of mental process. "Variations in genetic background may affect both MPO levels and the risk of mental disorders." (PMID 40401059, 2025).
mesenchymal tumors (1 paper, 2013). "Further immunohistochemical studies, including lysozyme and myeloperoxidase (MPO), CD68, and chloroacetate, were used to detect their myeloid origins and exclude lymphoreticular tumors and mesenchymal tumors." (PMID 24148102, 2013).
microcephaly (1 paper, 2015). A congenital or acquired developmental disorder in which the circumference of the head is smaller than normal for the person's age and sex. "The risk of microcephaly was increased in newborns with hyperEPO+ISSI (ISSI defined by CRP, SAA, MPO, IL-6, TNF-α, TNF-R2, IL-8, MCP-1, ICAM-1, E-SEL, red), often more prominently than for ISSI alone." (PMID 25793991, 2015).
microscopic colitis (1 paper, 2023). Inflammation of the colon that is only apparent by microscopic examination. "The use of fecal neutrophil enzymes, including fecal calprotectin, fecal lactoferrin, and fecal myeloperoxidase, has been studied in patients with microscopic colitis." (PMID 37445477, 2023). "Myeloperoxidase has been shown to be increased in IBD and has been studied in patients with microscopic colitis." (PMID 37445477, 2023).
Miscarriage (1 paper, 2020). A pregnancy that ends at a stage in which the fetus is incapable of surviving on its own, defined as the spontaneous loss of a fetus before the 22th week of pregnancy. "The concentrations of cell-free DNA (cfDNA) and MPO, both indirect markers of NETs, were assessed in the serum of women who have had a miscarriage." (PMID 32753622, 2020). "All remaining women who had suffered a miscarriage and whose placental tissue showed the presence of NETs markers: MPO, H2A, H2B, and H3 histones were included in the NETs-positive group." (PMID 32753622, 2020). "According to the present study's results women who had a miscarriage showed higher levels of MPO than those who did not." (PMID 32753622, 2020).
morbid obesity (1 paper, 2024). An excess of body weight, normally defined as an individual with a body mass index greater than 35 or a body weight greater than one hundred percent of ideal body weight. "This gender-related distribution of morbid obesity likely plays a key role in the observed differences in MPO levels." (PMID 39857642, 2024).
Moyamoya disease (1 paper, 2017). Moyamoya disease (MMD) is a rare intracranial arteriopathy involving progressive stenosis of the cerebral vasculature located at the base of the brain causing transient ischemic attacks or strokes. "After comprehensive examinations, we also found the presence of myeloperoxidase antineutrophilc cytoplasmic antibodies (MPO-ANCA) and cerebral involvement of asymptomatic multiple intracranial vasculopathy which we highly suspected it as moyamoya disease." (PMID 29390537, 2017).
MRSA pneumonia (1 paper, 2013). "Similar findings were found with pulmonary neutrophil infiltration as MRSA pneumonia yielded an increase in MPO activity which was not worsened in radiation combined injury." (PMID 24204769, 2013).
muscular dystrophies (1 paper, 2024). "The myeloperoxidase (MPO) enzyme produced by neutrophils, monocytes, and macrophages serves as a marker for quantifying inflammation linked to muscle degeneration in muscular dystrophies." (PMID 39834392, 2024).
nasopharyngeal carcinoma (1 paper, 2010). A carcinoma arising from the nasopharyngeal epithelium. "Although numerous studies have examined the association of the polymorphisms for CYP2E1, GSTP1, MPO and NQO1 genes with various tumors, very few have investigated the associations between variants of these genes and the risk of nasopharyngeal carcinoma." (PMID 20663217, 2010).
necrosis (1 paper, 2025). The phenotypic observation that death has occurred in groups of cells or in one or more tissues due to external factors, such as infection, toxins, mechanical trauma, loss of blood supply and other injuries (e.g. corrosion or burning). "Circulating proteins like soluble LOX-1 (sLOX-1), pregnancy-associated plasma protein A (PAPP-A), and myeloperoxidase (MPO) outperform troponin in predicting plaque instability by detecting early vascular inflammation and rupture before myocardial necrosis occurs." (PMID 41511355, 2025).
non-Hodgkin lymphoma (1 paper, 2025). Distinct from Hodgkin lymphoma both morphologically and biologically, non-Hodgkin lymphoma (NHL) is characterized by the absence of Reed-Sternberg cells, can occur at any age, and usually presents as a localized or generalized lymphadenopathy associated with fever and weight loss. "Immunohistochemistry (IHC) is essential for accurate diagnosis, with MPO, lysozyme, and CD68 confirming myeloid lineage and excluding mimickers such as high-grade non-Hodgkin lymphomas." (PMID 40951125, 2025).
Onchocerca volvulus infection (1 paper, 2018). "This is similar to an earlier study on Onchocerca volvulus infection that showed that the plasma level of MPO was correlated with ANC." (PMID 29479356, 2018).